IL10 (interleukin 10)
Diseases named in the same sentence as IL10 in open-access papers (continued):
Sharing a sentence is not in itself a finding about the gene and the disease.
glioma (continued). "Therefore, the result that ABCA1 is positively associated with IL-10 confirms the positive correlation of ABCA1 with M2 macrophage infiltration in glioma." (PMID 37749600, 2023). "Glioma-associated macrophages could secrete cytokines such as IL-10 and TGF-β, which decrease the activities of immune cells and promote tumorigenesis." (PMID 35281049, 2022). "Several authors have linked the gene IL-10 to glioma cell proliferation." (PMID 36009467, 2022). "The immune microenvironment is composed of glioma-associated immune cells, such as microglia, macrophages, and B cells, and immunoregulatory factors, such as interleukin (IL)-6, IL-10, and transforming growth factor β (TGF-β), which regulate the progression of glioma." (PMID 35982954, 2022). "Moreover, down-regulation of miR-98 has been associated with the invasive possibility of glioma, and several target genes, such as interleukin 10 (IL-10) and high-mobility group A2 (HMGA2), have been identified." (PMID 33393590, 2021). "IL-10 messenger RNA has been seen in gliomas, with higher levels associated with higher grades." (PMID 31973059, 2020). "Previous studies reported that glioma cells could stimulate monocytes and glioma-associated macrophages to produce IL-10, which in turn significantly increases PD-L1 expression in monocytes and tumor-infiltrative macrophages." (PMID 30687086, 2018). "Therefore, we hypothesized that high RP2 expression could cause poor prognosis in glioma by affecting the infiltration of Macrophages and the secretion of IL-10 and TGF-β by Macrophages." (PMID 37602882, 2023). "It has been demonstrated that the release of CMV interleukin-10 (CMV IL-10), a homolog of human IL-10 that is associated with higher-grade gliomas and may exacerbate a tumor’s invasive potential, is induced upon the in vitro infection of glioma cancer stem cells by human CMV." (PMID 33668202, 2021). "Furthermore, increased IL-10 expression levels are associated with glioma malignancy." (PMID 29389898, 2018). "However, we found that the IL-10 rs1800871 C/T genotype was associated with increased OS in low-grade glioma cases (3-year survival rate = 13.1%, median survival = 12 months, Log-rank p = 0.019, HR=0.745, 95% CI=0.573–0.969, p = 0.028), but not high-grade cases." (PMID 27811370, 2016). "STAT3 is turned on by signals including IL-6, IL-10, epidermal growth factor and fibroblast growth factor, making it a key player in glioma immune evasion." (PMID 41157253, 2025). "NS inhibits the expression of pro-inflammatory mediators and stimulates that of IL-10 in glioma and fibroblast cells." (PMID 40076857, 2025). "Our bioinformatic analysis of patients with glioma seems to confirm our in vitro and in vivo findings connecting FH expression with changes in the immunomodulatory molecules, including IL10, in the microenvironment." (PMID 39378431, 2025). "In gliomas, microglia frequently adopt the M2 phenotype, which promotes angiogenesis and tumor progression by secreting factors such as IL-10 and transforming growth factor β (TGF-β)." (PMID 40497976, 2025). "These recruited immune cells simultaneously secrete cytokines and growth factors that can stimulate glioma proliferation and angiogenesis, such as IL10 and VEGF." (PMID 41034696, 2025). "These cells contribute to the immunosuppressive environment of glioblastoma (GBM) by producing interleukin-10 (IL-10) and transforming growth factor-β (TGF-β), potentially making the gut microbiota a risk factor for gliomas." (PMID 39940440, 2025). "Immunosuppressive cytokines such as transforming growth factor-beta (TGF-β) and IL-10 inhibit their maturation, while glioma-derived exosomes disrupt their differentiation." (PMID 40621473, 2025). "Glioma cells and infiltrating immune cells evade immune surveillance by secreting immunosuppressive factors, such as IL-6, IL-10, TGF-β, and prostaglandin E2, whose expression is regulated by tumor-derived growth factors." (PMID 41426972, 2025).
glioma (continued). "In vitro experiments have demonstrated that knockdown of TIM-1 expression inhibited the proliferation, migration, and invasion of glioma (U87, U251) cells and decreased the levels of TGF-β1, IL-6, IL-4, and IL-10 in gliomas." (PMID 38831760, 2024). "Elevated levels of these immunosuppressive mediators correlate with glial tumor grade: high-grade gliomas express elevated IL-10 and TGF-β levels." (PMID 39200114, 2024). "Expression of PD-L1 in circulating TAMs and monocytes can be upregulated by glioma cells via autocrine/paracrine IL-10 signaling." (PMID 39452154, 2024). "The combination of IL10 with its receptor IL10R expressed in glioma cells would further promote the proliferation, migration, and invasion of glioma." (PMID 38322416, 2024). "Combined assessment of the MYD88 L265P mutation, IL‐10 levels and PCR for Ig heavy chain variable (IgVH) rearrangement in the CSF allows efficient discrimination of PCNSL from glial neoplasms and non‐neoplastic disorders of the CNS." (PMID 38836097, 2024). "The silencing of Prkar1a results in the upregulation of immunosuppressive factors TGF-β and IL-10 that support a favorable environment for glioma progression." (PMID 37046685, 2023). "Glioma cells secrete cytokines like TGFβ, IL-10, VEGF, and CSF-1, which inhibit the differentiation of DCs." (PMID 37781367, 2023). "TAMs enriched in the glioma TME can secrete cytokines such as IL-10 and TGFβ, which decrease the activities of immune cells and promote glioma progression." (PMID 37441589, 2023). "According to reports, M2 Macrophages in glioma can directly suppress the immune response by secreting IL-10, TGF-β, and other immunosuppressive molecules." (PMID 37602882, 2023). "Glioma cells can upregulate PD-L1 expression in circulating monocytes and TAMs through autocrine/paracrine IL-10 signaling." (PMID 37705736, 2023). "And our results did confirm that the high expression of RP2 is positively associated with IL-10, TGF-β in glioma." (PMID 37602882, 2023). "The IL-10 and TGF-β enriched immunosuppressive TME of gliomas leads to loss of MHC expression on microglia." (PMID 37686020, 2023). "In the first 24 h, glioma-neutrophil cultures produced high amounts of IL-8 and TNFα, slightly increased amounts of IL-12p70, and low to zero levels of IL-1β, IL-6, and IL-10." (PMID 37292196, 2023). "has discovered co-culture of naive T cell with glioma-associated MDMs can induce a differentiation into TGFBI and IL-10 secreted CD4+ Treg cell." (PMID 36761752, 2023). "Cytokine networks in the glioma microenvironment include prostaglandins E2, IL-6, IL-10, and TGF-β, each of which inhibits T cell proliferation and activation." (PMID 37375698, 2023). "The administration of MWCNTs led to heightened macrophage infiltration into glioma cells, resulting in a time- and dose-dependent increase in tumor cytokine levels, particularly IL-10." (PMID 37799472, 2023). "Concurrently, glioma cells can also secrete the immunosuppressive factor interleukin-10 (IL-10) via an autocrine or paracrine pathway and microglial PD-L1 expression is elevated, thus promoting the formation of an immunosuppressive tumor microenvironment." (PMID 37700840, 2023). "TGFB1, VEGFA, ARG1, and IL10 are secreted immunosuppressive factors in glioma, while CD70 is a glioma cell-surface immunosuppressive factor." (PMID 37891828, 2023). "For example, glioma cells secrete or induce secretion of the immunosuppressive cytokines IL-10 and TGF-β, which can increase the threshold for T cell activation, and directly suppress their anti-tumor activity, allowing for tumor proliferation." (PMID 36768342, 2023). "FGL2, IL10, TGFB1, and VEGFA were secreted immunosuppressive molecules in glioma and were consistently upregulated in high-risk group from all four datasets." (PMID 37864127, 2023). "Differentiation of DCs is inhibited by cytokines secreted by glioma cells, such as IL‐10, IL‐6, prostaglandin E2 (PGE2) and VEGF." (PMID 36464889, 2023).
glioma (continued). "Paradoxically, IL-10 has also been demonstrated to have anti-glioma effects in a mouse model when expressed in conjunction with other cytokines, such as IL-2." (PMID 36768342, 2023). "Our data demonstrates that glioma patients present an important cytokine-related worse outcome, especially regarding IL-1β and IL-10." (PMID 37292196, 2023). "IL-10 secreted by microglia in gliomas is an immunosuppressive cytokine and correlates with the malignancy of gliomas." (PMID 37700840, 2023). "The lack of appropriate T-cell activation in TME is because antitumor T-cell responses are repressed by cytokines secreted by glioma cells, such as TGFβ and IL-10." (PMID 35269652, 2022). "HGGs expresses a variety of immune-suppressive cytokines, including TGF-β, IL-10, IL-4, IL-6, and IL-13, all of which impede the anti-glioma immune response directly or indirectly." (PMID 36186781, 2022). "To study the potential involvement of MDSCs in FAT1-mediated immunosuppression in tumors, we studied the expression of surrogate markers of MDSCs, namely, PD-L1, PD-L2, and IL-10 in gliomas." (PMID 35720420, 2022). "This renounces the antitumor activity and contributes to glioma invasion, releasing multiple cytokines, i.e., IL-1β, IL-6, IL-8, IL-10, and TNF-α." (PMID 35454935, 2022). "KPNA 2 is regarded as a glioma marker, and IL-10 can upregulate KPNA 2 in order to enhance the proliferation and invasion of glioma cells." (PMID 36497459, 2022). "Studies suggested that B. fragilis can induce the differentiation of IL10-secreting Tregs, which can impair the anticancer immunity of Th1 and are related to the progression and invasiveness of gliomas." (PMID 36003766, 2022). "The levels of sHLA-G are also highly negatively correlated with the concentration of pro-inflammatory cytokine IL-6 and positively with the IL-10/IL-6 ratio in plasma of glioma patients." (PMID 35626255, 2022). "IL10 binds to its corresponding receptor, causing STAT3 phosphorylation through JAK1 and STAT2, which stimulates the proliferation of glioma cells." (PMID 35741689, 2022). "The Spearman correlation analysis results suggested that the immune marker sets of Treg (FOXP3, CCR8, TGFβ1), TAM (CCL2, CD68, IL-10), and MDSC (CD33, ITGAM, FUT4) were significantly associated with the PROS1 expression in glioma." (PMID 36685506, 2022). "Prostaglandin E2 (PGE2) from glioma cells was observed to boost the production of IL-10 by DCs, resulting in the development of a regulatory response in CD4 T cells and a reduction in effector lymphocyte stimulation." (PMID 35269652, 2022). "The presence of the IL10 protein in glioma tissues was verified using the human protein atlas (HPA)." (PMID 35741689, 2022). "Another group showed that murine bone marrow-derived DCs co-cultured with glioma cells show enhanced IL-12 and decreased IL-10 secretion in the presence of diclofenac after stimulation with R848." (PMID 36227963, 2022). "The expression level of IL-10 in glioma patients was higher than that in the normal population, and the expression level increased significantly with the increase of the malignant degree of glioma." (PMID 36387186, 2022). "Functionally, GDEs and miR-3591-3p significantly induced M2 macrophage polarization and increased the secretion of IL10 and TGFβ1, which in turn promoted glioma invasion and migration." (PMID 36085418, 2022). "When exposed to the exosomes released by glioma cells, the expansion of BMDCs with MDSCs phenotype was induced in healthy BMDCs, secreting IL-10, TGF-β, Fas-ligand and B7-H1 to inhibit the activation of T lymphocytes." (PMID 34211978, 2021). "Co-culture of glioma cells and NKTs showed miR-92a expressing in glioma cells played a key role in inducing the elevated expression of IL-6 and IL-10 in NKTs." (PMID 34603399, 2021).
glioma (continued). "Gliomas result in the upregulation of B7-H1 expression in tumor-infiltrative macrophages and circulating monocytes by modulating autocrine and paracrine IL10 signaling, which produces an immunosuppressive phenotype." (PMID 33987093, 2021). "In the presence of glioma cells, the expression of IL-10 tended to be increased in both THP-1 and HMC3 cells." (PMID 33670244, 2021). "IL-10 produced by glioma cells has also been found to play a role as an initial chemotactic agent to recruit monocytes and a driver of immunosuppressive loops between cancer cells and macrophages within the tumor microenvironment." (PMID 33917598, 2021). "IL-10 can be produced from the glioma directly or gliomas can stimulate the production of IL-10 by macrophages and microglia." (PMID 32542437, 2021). "As a possible factor linking miR-181b to IL10, we tested the transcriptional factor c-Fos, which binds the IL10 promoter enhancing IL10 transcription in T cells and was validated as a direct miR-181b target in glioma cells." (PMID 33445508, 2021). "Treatment of glioma activated microglial cells with mTOR blockers promoted M2 differentiation to cytotoxic M1 phenotype, as evidenced by decreased Arg-1 and IL-10 gene expression." (PMID 34439380, 2021). "Higher levels of PRDM1 were observed in high-HIF1A-expression GBM and lower-grade glioma, while higher levels of NFAT and IL10 were only observed in lower-grade glioma." (PMID 34305618, 2021). "Meanwhile, the IL‐4 and IL‐10 released by microglia have anti‐inflammatory effects in the glioma environment." (PMID 33300633, 2021). "Conversely, the M2 phenotype is considered cytoprotective, immunosuppressive, and protumorigenic, occurring after M-CSF (expressed by glioma cells, as well as normal human astrocytes), IL-4, IL-10 and/or IL-13 exposure." (PMID 32542437, 2021). "Treg is a T cell subtype responsible for anti-inflammatory and immune tolerance, secreting high levels of inhibitory cytokines including TGF-β and IL-10, which allowed glioma cells to escape the cytotoxic damage of CTLs in TME." (PMID 34211978, 2021). "Together, these data suggest that glioma cells can stimulate the expansion of MDSCs by secreting numerous well-studied factors (IL-6, IL-10, VEGF, PGE-2, GM-CSF, and TGF-β2)." (PMID 32391020, 2020). "CSF2 depletion from both LN18 and U87 glioma cells blocked up-regulation of the anti-inflammatory IL10 expression and led to induction of IRF7 and IL1β mRNA levels in stimulated microglia." (PMID 32390004, 2020). "We show that LN18 and U87 glioma polarise primary human microglia cultures towards the pro-tumorigenic, immunosuppressive phenotype (up-regulation of IL10, MYC) in vitro." (PMID 32390004, 2020). "GCM from control LN18 and U87 cells (shNeg) induced IL10 and MYC expression in human microglia, while knockdown of CSF2 in glioma cells reverted IL10 mRNA to the basal levels." (PMID 32390004, 2020). "Cytokines released from glioma cells, such as IL-10, have the potential to encourage synapse forming activities in microglia, yet this phenomenon has yet to be clearly defined in pre-clinical models." (PMID 33187183, 2020). "In the current study, we found that IL-8 and IL-10 levels were elevated in patients with a higher grade of glioma (WHO grade IV vs. grade II–III)." (PMID 31847343, 2019). "Incomplete T-cell activation in the glioma microenvironment is also due to the fact that anti-tumor T-cell responses are also suppressed by cytokines TGF-β and IL-10 produced by glioma cells." (PMID 31225500, 2019). "In the case of GBs, glioma cells are able to stimulate GAMs to produce immunosuppressive molecules, such as IL-10, metalloproteinases (MMPs), chemokines as monocyte chemotactic protein-1 (CCL2), and ARG-1, that stimulate the tumor growth." (PMID 30123112, 2018).
glioma (continued). "Since both MDSCs and TAMs around the glioma microenvironment express high levels of IL-10 and are skewed toward an immunosuppressive phenotype by IL-10, it is likely that MDSCs and TAMs promote polarization of each other in glioma." (PMID 30619286, 2018). "When M2 TAMs release low levels of IFN-γ and high levels of IL-10, microglia act as potent regulatory T cells (Tregs) inducer and further supports immune suppression in the glioma environment." (PMID 30619286, 2018). "Glioma cells produce various inflammatory mediators, such as IL-1β, IL-6, IL-8, IL-10, MCP-1, and MIP." (PMID 28881826, 2017). "Previous literature characterizes IL10 as immunosuppressive and finds only positive associations between serum IL10 or genetic expression of IL10RB and glioma." (PMID 28594935, 2017). "Beside, IL-10 mRNA correlate with tumor grade, increases cell proliferation and motility of glioma cells and is mainly concentrated in microglia and macrophages which contribute to tumor progression though the inhibition of the patient’s immune response." (PMID 28107450, 2017). "A separate study found that highly invasive glioma tissues expressed IL-10 at higher levels than more localized gliomas." (PMID 28346397, 2017). "Glioma (brain tumor) cells secrete immunosuppressive cytokines such as transforming growth factor-beta, prostaglandin E, and interleukin (IL)-10, and are also highly capable of evading the host immune system." (PMID 30970690, 2017). "In the present study, we selected one single nucleotide polymorphism (SNP) in IL-10 and one in PRKDC, each of which was reportedly associated with glioma risk." (PMID 27811370, 2016). "We found that the influence over glioma cells exerted by IL-10 can be significantly abolished after blockage of IL-10, relative to control group." (PMID 27765933, 2016). "We showed that it is IL-10 secreted from M2 macrophage that promotes the proliferation of glioma cells, which was in agreement with previous studies." (PMID 27765933, 2016). "We analyzed the associations of one IL-10 and one PRKDC single nucleotide polymorphism with patient clinical factors in 481 glioma patients using Cox proportional hazard models and Kaplan-Meier curves." (PMID 27811370, 2016). "Interleukin-10 (IL-10) and DNA repair gene PRKDC mutations are implicated in the development of multiple human cancers, including glioma." (PMID 27811370, 2016). "We investigated associations between IL-10 and PRKDC gene polymorphisms and prognosis in low- and high-grade glioma patients." (PMID 27811370, 2016). "Instead, TAMs from glioma secreted or expressed some cytokines, such as IL-10, transforming growth factor beta (TGF-β), and other solute factors." (PMID 27765933, 2016). "IL-10 was shown to be most significantly higher among the cytokines secreted by M2 macrophage, which was fully congruent with early reports in glioma." (PMID 27765933, 2016). "Although previous association studies linked IL-10 and PRKDC genetic polymorphisms with glioma risk, few focused on the effects of these alterations on glioma patient prognosis." (PMID 27811370, 2016). "After WHO grade stratification, we found that rs1800871 in IL-10 correlated with increased OS in low-grade glioma cases, while rs7003908 in PRKDC correlated with poor prognosis in high-grade cases." (PMID 27811370, 2016). "Mechanistically, we found that it is IL-10 from M2 type macrophage that was displayed to promote growth through activation of JAK/STAT signaling pathway in glioma cells in vitro." (PMID 27765933, 2016). "IL-10 was described to be produced by primary cultured glioma cells as well as glioma cancer stem cells." (PMID 25793261, 2015). "IL10, an upregulated cytokine in our study, was shown to be expressed in glioma by few studies and functions to inhibit antitumor response while promoting proliferation and motility." (PMID 26390214, 2015).